NPPA (natriuretic peptide A)
Diseases named in the same sentence as NPPA in open-access papers (continued):
Sharing a sentence is not in itself a finding about the gene and the disease.
ischemic cardiomyopathy (2 papers, 2014 to 2022). Ischemic cardiomyopathy is a cardiomyopathy in which a weakness in the muscle of the heart due to inadequate oxygen delivery to the myocardium with coronary artery disease being the most common cause. "Increased NPPA expression was detected in human ischemic cardiomyopathy and administering ANP reduced the infarct size and improved the outcome in patients with an AMI." (PMID 35053121, 2022).
basal cell carcinoma (1 paper, 2022). A carcinoma involving the basal cells. "Interestingly, the terms “basal cell carcinoma” and “TGF-β signaling pathway” were enriched in the KEGG pathways of NPPA, OMD, and PRELP, and acted as the positive pathways." (PMID 36544902, 2022).
Brugada syndrome (1 paper, 2022). A genetically heterogeneous condition characterized by complete or incomplete right bundle branch block accompanied by ST elevation in leads V1-V3. "The truncated mutations of NEBL (p.R882X) and NPPA (p.R107X) may induce Brugada syndrome by abnormally affecting cardiac sodium channel." (PMID 36303204, 2022). "Therefore, we proposed that truncated mutations of NPPA (p.R107X) and NEBL (p.R882X) may induce Brugada syndrome by aberrantly affecting the cardiac sodium channel, similar to loss-of-function of the sodium channel." (PMID 36303204, 2022).
congenital heart malformation (1 paper, 2023). A disease that has its basis in the disruption of heart development. "Interestingly, the expression quantitative trait loci (eQTL) analysis from the GTEx Project showed that congenital heart malformation risk-associated SNP rs56153133 was associated with the expression of NPPA in atrial appendage tissue (P = 1.86E − 05)." (PMID 36745292, 2023).
gastroschisis (1 paper, 2024). Gastroschisis is marked by viscera protruding, without a covering sac, from the fetal abdomen on the right lateral base of the umbilicus. "Besides ICAM1, the study from the Torfs group also identified a heterozygous/homozygous variant of NOS3, NPPA, ADD1, SERPINE1, and SELE, genes involved with cell–cell interactions, inflammation, or blood pressure, associated with gastroschisis." (PMID 39728087, 2024).
glioma (1 paper, 2021). A benign or malignant brain and spinal cord tumor that arises from glial cells (astrocytes, oligodendrocytes, ependymal cells). "Consistently, we observed that the expression of NPPA was suppressed in various tumor tissues and was only overexpressed in lower grade glioma." (PMID 34616853, 2021).
ventricular tachycardia (1 paper, 2007). A disorder characterized by an electrocardiographic finding of three or more consecutive complexes of ventricular origin with a rate greater than a certain threshold (100 or 120 beats per minute are commonly used). "Thus ventricular tachycardia caused a short-term increase of BNP and atrial natriuretic peptide as a result of atrial and ventricle wall tension." (PMID 17957267, 2007).
viral myocarditis (1 paper, 2021). Myocarditis that is caused by an infection with a viral agent. "The DEGs for cardiomyocytes were primarily involved in viral myocarditis, cell adhesion molecules, and regulation of lipolysis in adipocytes (e.g., FABP4, NPPA, etc.)." (PMID 34514716, 2021).
cardiovascular disease (67 papers, 2010 to 2026). "(I) For pathogenic SNVs in non-coding regions, we queried chr1:11845727 T > G (GRCh38), located in the 3′ UTR (untranslated regions) of the NPPA gene, which is associated with cardiovascular disorders." (PMID 37956311, 2024). "Simultaneously, our gene-level annotation data indicated that NPPA is associated with cardiovascular diseases and is highly expressed in the heart." (PMID 37956311, 2024). "To date, variants in the NPPA gene, encoding prepro-ANP, have been shown to be a key determinant in blood pressure levels and risks for cardiovascular disease." (PMID 37636304, 2023). "Variants of the NPPA gene, encoding the ANP precursor, have been associated with blood pressure levels and risk of cardiovascular diseases." (PMID 36232551, 2022). "Polymorphisms in the NPPA gene, encoding the ANP precursor, have been associated with blood pressure levels and cardiovascular disorders." (PMID 35892957, 2022). "Of the top 50 up-regulated hCM-specific genes we analyzed, 27 of them (54%) showed associations with at least one known cardiovascular diseases and 5 of them (NPPB, TNNT2, NPPA, RYR2, and PLN) were linked to more than 10 different types of cardiovascular diseases." (PMID 24474197, 2014). "Overall, previous studies have elucidated the pathological roles or diagnostic values of NPPA, OMD, and PRELP in different cardiovascular diseases, but have not yet involved DCM with HF." (PMID 36544902, 2022).
heart disease (41 papers, 2009 to 2026). "Because NPPA upregulation is a hallmark of heart disease and is associated with epigenetic changes, we assessed chromatin rewiring at the NPPA locus in F-LV-CM." (PMID 41526351, 2026). "In line with functional findings, LV gene expression levels of Nppa, encoding natriuretic peptide A (ANP), a well-established marker for heart disease, progressively increased with HF progression in PLN-R14 Δ/Δ mice to 16-, 40- and 60-fold elevations in 5-, 6- and 8-week-old mice, respectively." (PMID 35269571, 2022). "Atrial natriuretic peptide and BNP levels are consistently elevated in heart disease in patients as well as in experimental models of heart disease, and are consistently linked to severity and progression of disease." (PMID 22943504, 2012). "Taken together, these elevated atrial natriuretic peptide and BNP levels in heart disease could be a protective attempt by the myocardial tissue to limit excess fibrotic deposition, tissue injury and adverse remodeling." (PMID 22943504, 2012).
cancer (33 papers, 2011 to 2025). A tumor composed of atypical neoplastic, often pleomorphic cells that invade other tissues. "The expression pattern of NPPA across various human tissues and cancer types has been demonstrated, and NPPA is simultaneously downregulated in cancer tissues." (PMID 34616853, 2021).
tumor (30 papers, 2009 to 2025). "We compared the expression pattern of NPPA in both normal and malignant tumor tissues with IST Online." (PMID 34616853, 2021). "Compared with the free PTX in tumor tissues in the Taxol treatment group, the level of NPPA-PTX was significantly lower than that of free PTX." (PMID 27366947, 2016). "It has been shown that CAMTA 1 can activate the expression of the anti-proliferative cardiac hormone natriuretic peptide A (NPPA) in the heart and is recognised as a tumor suppressor." (PMID 24278182, 2013). "Specifically, the level 3 classifier shows strong correlations among genes like KRT5, S100A7, KRT16, S100P, and LY6D, while the level 6 classifier exhibits similar patterns with GPR17, RGR, and NPPA, highlighting the complex interplay of genes in tumor subtype classification." (PMID 40802546, 2025). "Also, the receptor for natriuretic peptide A and B (natriuretic peptide receptor A, NPRA) has been reported to be involved in immune and inflammatory reactions as well as in tumor growth." (PMID 29457529, 2018). "At 4 and 8 h, no NPPA-PTX was detected in the MDA-MB-231 tumor tissues at 4 and 8 h time points, also indicating that NPPA-PTX was completely transformed into dissociated PTX." (PMID 27366947, 2016). "FGF17, natriuretic peptide A (NPPA), SHC2, and WAP, follistatin/kazal, immunoglobulin, kunitz, and netrin domain containing 1 (WFIKKN1) was not expressed or at a minimal level in tumor tissues." (PMID 34335699, 2021).
NPPA also shares sentences with these, for which no sentence is quoted: congestive heart failure (62 papers); Sepsis (32); hypertrophy (24); Insulin resistance (23); Ventricular hypertrophy (18); pulmonary hypertension (17); coronary artery disease (16); chronic kidney disease (14); Arrhythmia (13); infection (13); Anxiety (12); endothelial dysfunction (11); essential hypertension (11); renal diseases (11); lung carcinoma (10); acute kidney injury (9); ischemia (9); pneumonia (9); acute myocardial infarction (8); hypertrophic cardiomyopathy (8); metabolic disease (8); prostate carcinoma (8); asthma (7); colorectal cancer (7); diabetic cardiomyopathy (7); renal failure (7); amyloidosis (6); depression (6); Mitral regurgitation (6); nephrotic syndrome (6).
A further 192 diseases each share a sentence with NPPA in 6 papers or fewer.